MCHR2 (melanin concentrating hormone receptor 2)
Description:
G protein-coupled receptor for the neuropeptide melanin-concentrating hormone (MCH). Upon ligand binding, couples to G(q/11), leading to activation of phospholipase C and intracellular calcium mobilization. The physiological roles mediated by this receptor remain unclear, and its contribution to specific biological processes has not been conclusively established (Probable). Expression of this receptor is restricted to the brain of non-rodent mammals; a functional MCHR2 gene is absent or pseudogenized in rodents (By similarity).
Synonyms: MCH-R2; MCHR-2; MCH2; MCH2R; GPR145; SLT; GPRv17; MCH-2R
Tractability: Small molecule: a high-quality ligand is known; it belongs to a druggable protein family. Antibody: its Gene Ontology location is reachable by antibodies, with high confidence; UniProt places it where antibodies can reach, with medium confidence; UniProt predicts a signal peptide or a membrane-spanning region. PROTAC: a small molecule that binds it is known.
Target class: Peptide receptor (family A GPCR); Short peptide receptor (family A GPCR); MCH receptor; Family A G protein-coupled receptor; Membrane receptor
Chemical probes: CHEMBL1934130
Gene: Protein-coding gene on chromosome 6 (99,918,519 to 99,994,247, reverse strand). Ensembl gene ENSG00000152034.
Subcellular location: Cell membrane
Subcellular location (Human Protein Atlas): Plasma membrane; Basal body; Nucleoplasm; Primary cilium tip; Vesicles
Pathways (Reactome):
Signal Transduction: G alpha (i) signalling events; G alpha (q) signalling events; Peptide ligand-binding receptors
Gene Ontology:
Molecular function: melanin-concentrating hormone receptor activity; protein binding; galanin receptor activity; G protein-coupled receptor activity
Biological process: G protein-coupled receptor signaling pathway; phospholipase C-activating G protein-coupled receptor signaling pathway; neuropeptide signaling pathway
Cellular component: plasma membrane; membrane
Genetic constraint (gnomAD): Loss-of-function variants: 17 observed, 26.22 expected, observed/expected ratio (o/e) 0.65, 90% interval 0.44 to 0.97. The upper end of that interval is the gene's LOEUF score, 0.97, which puts it in group 4 of 6, group 1 being the genes least tolerant of losing a copy. Missense variants: 382 observed, 424.01 expected, observed/expected ratio (o/e) 0.9, 90% interval 0.83 to 0.98. Synonymous variants: 148 observed, 153.53 expected, observed/expected ratio (o/e) 0.96, 90% interval 0.84 to 1.11.
Homologues: Orthologues: chimpanzee MCHR2 (99% identical), macaque MCHR2 (97% identical), pig MCHR2 (90% identical), dog MCHR2 (88% identical), tropical clawed frog mchr2 (74% identical), zebrafish MCHR2 (60% identical), zebrafish mchr2a (58% identical). Paralogues in human: MCHR1 (34% identical), PRLHR (24% identical), GPR19 (21% identical), NPY2R (21% identical), TACR2 (21% identical), GPR83 (20% identical), NPY4R (20% identical), NPY4R2 (20% identical), TACR1 (20% identical), NPY1R (19% identical), TACR3 (19% identical), MTNR1A (19% identical), and 21 more.
Diseases named in the same sentence as MCHR2 in open-access papers:
MCHR2 is named in the same sentence as 20 diseases in open-access papers, as found by Europe PMC text mining. Sharing a sentence is not in itself a finding about the gene and the disease. The quoted sentences say what the papers report.
Obesity (7 papers, 2013 to 2025). Accumulation of substantial excess body fat. "SIM1 is involved in the regulation of energy homeostasis, and KIF1BP and MCHR2 are involved in the regulation of food intake, which in turn affects obesity risk." (PMID 32355558, 2020). "A recent genetic analysis looking for associations of MCHR2 single nucleotide polymorphisms (SNPs) with severe obesity of children implied a possible involvement of MCHR2 in food intake abnormalities in obese children." (PMID 25505557, 2013). "However, MCHR2 has been reported to be associated with human obesity and a cattle growth trait, making it a plausible candidate pleiotropic gene that controls presoma traits." (PMID 30562943, 2018). "Moreover, the only reported study that associated MCHR2 with obesity also observed an age-dependent genetic susceptibility in obesity, with the younger being more concerned." (PMID 26461262, 2015). "Validation of an association of MCHR2 with obesity requires replication in other cohorts." (PMID 23626585, 2013). "Even though MCHR2 is not expressed in rodents, a recent study showed that induction of MCHR2 expression in mice protected against diet-induced obesity." (PMID 26461262, 2015). "Cynomolgus monkey expresses both MCHR1 and MCHR2 and some become obese with age and a sedentary lifestyle, with parallels to human obesity." (PMID 25505557, 2013). "Amongst other genes that link depression with obesity, melanin-concentrating hormone receptor 2 (MCHR2), proprotein convertase subtilisin/kexin type 9 (PCSK9), and apolipoprotein A5 (APOA5) may be mentioned, as genes involved in energy-related processes." (PMID 41375608, 2025). "MCHR2 has been described as one of the components acting in the hypothalamic regulation of food intake, a system of regulation involved early in the development of obesity." (PMID 26461262, 2015). "None of the MCHR2 variants showed an association with adult severe obesity, but the A76A SNP was associated with severe obesity (P = 0.01) and overeating in obese children (P = 0.02)." (PMID 23626585, 2013). "The association between MCHR2 variation and human obesity was investigated in 141 obese children and 24 non-obese adult subjects by DNA sequencing, and by case-control analyses using 628 severely obese children and 1401 controls." (PMID 23626585, 2013). "This study provides new insights on the possible influence of MCHR2 and/or MCHR2-AS1 on obesity in psychiatric patients and on the pathophysiology of atypical depression." (PMID 26461262, 2015). "Transgenic mice expressing human MCHR2 have reduced food intake and body weight, whereas humans with deletions encompassing MCHR2 and an adjacent gene, Single-Minded Homolog 1 (SIM1), have increased appetite and obesity." (PMID 35271580, 2022). "Third, since humans also express MCHR2 in the hypothalamus, MCH signaling in humans may involve both MCHR1 and MCHR2, such that blockade of the MCHR1 alone may not be sufficient to achieve efficacy in obesity." (PMID 23626585, 2013).
depression (2 papers, 2015 to 2025). "MCHR2 CC or CT polymorphism is associated with higher BMI in individuals with either a past or present atypical depression diagnosis." (PMID 41375608, 2025). "Moreover, the significant interaction found between MCHR2/MCHR2-AS1 and BMI in population-based subjects with present and/or previous history of atypical depression but not non-atypical depression provides new clues to the pathophysiology of atypical depression." (PMID 26461262, 2015).
glioma (2 papers, 2017 to 2023). A benign or malignant brain and spinal cord tumor that arises from glial cells (astrocytes, oligodendrocytes, ependymal cells). "In high-grade gliomas, RYR2, MCHR2, FADS6, HTR2C, CMTM3, APH1A, and PFN1 genes are related to membrane function." (PMID 37239411, 2023).
Chronic colitis (1 paper, 2013). A chronic inflammatory disease of the large intestine (colon, cecum and rectum). "Taking into consideration that increased expression of human MCHR2 was found during intestinal inflammation, this observation might suggest differences in acute vs. chronic colitis, or perhaps that zebrafish MCHR1b may exhibit more functional homology to human MCHR2 in the zebrafish intestine." (PMID 24376661, 2013).
colitis (1 paper, 2013). Inflammation of the colon. "Since both MCH and its receptors were found to be upregulated in the intestine of patients with inflammatory bowel disease and of mice with TNBS-induced colitis, we subsequently examined mRNA levels of MCHR1b and MCHR2 in brain vs. gut and in response to TNBS treatment." (PMID 24376661, 2013). "Thus, in theory, zebrafish might represent a suitable model to study the role of MCHR2 in colitis, particularly in light of its intestinal regulation that we demonstrated in TNBS-exposed zebrafish." (PMID 24376661, 2013).
diabetes (1 paper, 2020). "Anyhow, lack of MCHR2 expression in rats, mice, and rabbits—the most popular animal models of diabetes—and its presence only in dogs, ferrets and rhesus monkeys supports another idea of using the canine animal model for a proper resemblance of human diabetes." (PMID 33348610, 2020).
Infertility (1 paper, 2022). "MCHR2 has been recognized as one of 371 clinically relevant genes for infertility as determined by high-resolution chromosome ideograms analysis." (PMID 36211460, 2022).
schizophrenia (1 paper, 2013). A major psychotic disorder characterized by abnormalities in the perception or expression of reality. "The evolutionary trade-off in this case would have been an increased prevalence of polymorphisms in melanotropin genes (MCHR1, MC5R, MCHR2) of risk for schizophrenia." (PMID 23847488, 2013).
tumor (1 paper, 2021). "At the molecular level, our bioinformatics analysis results suggested that HTR2C, TACR3, MCHR2 and GHSR might be LINC01296 targets through tumor microenvironment and phosphorylation regulation." (PMID 34515611, 2021).
MCHR2 also shares sentences with these, for which no sentence is quoted: alopecia areata (1 paper); autoimmune thyroid disease (1); binge eating disorder (1); cancer (1); chondrosarcoma (1); colon adenocarcinoma (1); esophageal carcinoma (1); inflammatory bowel disease (1); nicotine addiction (1); psychiatric disorder (1); systemic lupus erythematosus (1).